MC1R (melanocortin 1 receptor)
Diseases named in the same sentence as MC1R in open-access papers (continued):
Sharing a sentence is not in itself a finding about the gene and the disease.
cancer (continued). "We describe here our experience with the study design of an international pooled-analysis on Melanocortin-1 receptor gene, SKin cancer and Phenotypic characteristics (M-SKIP project)." (PMID 22862891, 2012). "Preliminary analysis of The Cancer Genome Atlas (TCGA) data suggested that active MC1R signaling might contribute to the pathogenesis of several cancers." (PMID 37679505, 2023). "Moreover, the upregulation of Cxcl9/10/11 in MC1R-depleted cancer cells resulted in significantly higher levels of Cxcl9/10/11 in the bulk MC1R-depleted tumors." (PMID 37714844, 2023). "There are many differences between cancer and normal tissues, the involvement of MC1R with other molecules in the regulation of organism function in cancer and normal tissues may also be inconsistent, and the specific reasons remain to be further explored." (PMID 34698109, 2021). "Based on our experience with the study design of the Melanocortin-1 receptor (MC1R) gene, SKin cancer and Phenotypic characteristics (M-SKIP) project, we describe the most important steps in planning and conducting a pooled-analysis of genetic epidemiological studies." (PMID 22862891, 2012). "Additionally, we noted elevated MC1R expression in HER2-negative cancer samples." (PMID 37679505, 2023). "Finally, cancer gene panel testing revealed additional pathogenic variants in two other (non-LS) genes, MC1R and NBN, that are independently associated with elevated risks of cancer in the branches of Family C that did not carry either MMR variant." (PMID 36612224, 2022). "Thus, although the living members of branches 6, 8, 10, and 11 in Family C did not have LS, carriers of the NBN and/or MC1R variants were counseled about the current state of knowledge of associated cancer risks and strategies for risk management." (PMID 36612224, 2022). "We also report the absence of intervention effects on cancer worry in either MC1R higher- or average-risk participants, and no changes in cancer worry between baseline and post-intervention, indicating that our intervention did not harm participants’ psychological well-being." (PMID 35845857, 2022). "Thus, further studies on MC1R in other cancers especially HBV-HCC are necessary." (PMID 32382578, 2020). "The authors synthesized and designed ligand-drug conjugates with the melanocortin 1 receptor (MC1R) agonist melanotan-II (MT-II) to couple a cytotoxic drug, camptothecin with low cancer resistance." (PMID 37569558, 2023). "To examine whether MC1R represses Cxcl9/10/11 expression in transplanted B16F10-dCas9 tumors in vivo, we performed RNA-seq of isolated cancer cells from B16F10-dCas9 tumors expressing the Mc1r sgRNA versus the NTC sgRNA." (PMID 37714844, 2023). "Extended genetic screening revealed additional germline variants within the cancer-associated NBN, MC1R, and PTPRJ genes in non-LS branches of the family in which several members also had cancer diagnoses." (PMID 36612224, 2022). "A functionally active MC1R pathway can play a distinct role in oncogenesis unique from what has been proposed previously, i.e. functional MC1R signaling does not always protect against, but can actively promote cancer incidence and/or progression." (PMID 23555311, 2013). "Genetic factors like polymorphisms of the melanocortin 1 receptor (MC1R) gene correlate with fairness of skin, UV sensitivity and enhanced cancer risk, however do not fully explain the diversity of UV responses, suggesting the possibility of epigenetic involvement in UV sensitivity and pathogenesis." (PMID 32737342, 2020).
infection (3 papers, 2012 to 2020). The state of being infected such as from the introduction of a foreign agent such as serum, vaccine, antigenic substance or organism. "We measured the temporal changes in NF-κB activation in relation to key components of the anti-inflammatory α-MSH/MC1-R signaling axis, and found that within the first 1 hr of infection KSHV induced a rapid increase in phosphorylated NF-κB p65 in MeWo cells." (PMID 24701351, 2014). "Furthermore, this region has been indicated as QTL of resistance to infection in dairy cattle, and revealed as a selection signature of cattle breeds with coat color phenotypes not determined by MC1R, such as Brown Swiss, Hanwoo and Nguni33,64,65." (PMID 32471998, 2020). "By contrast, MC1-R protein was induced almost immediately after infection of Mel1700 cells, but there was no appreciable impact on the already high baseline level of TRP-1; instead, there was a virus-induced increase in mRNA for MC1-R, POMC (the precursor of α-MSH), and xCT (gene name SLC7A11)." (PMID 24701351, 2014).
kidney diseases (2 papers, 2014 to 2015). "Importantly, it has been demonstrated that MC1R is expressed in the kidney cells and shown that treatment with MC1R agonists ameliorated kidney diseases in rats with passive Heymann nephritis." (PMID 25945350, 2015).
neurodegenerative disease (2 papers, 2014 to 2021). A disorder of the central nervous system characterized by gradual and progressive loss of neural tissue and neurologic function. "Furthermore, our study revealed a role for MC1R in the susceptibility to neurodegenerative diseases which may be related to its role in oxidative stress and inflammatory processes." (PMID 24742402, 2014). "Notably, RHC MC1R skin cells also showed up-regulated pathways related to neurodegenerative diseases." (PMID 24742402, 2014). "Unfortunately, the association between MC1R and PD is controversial, with multiple studies unable to replicate the finding, and to date, no strong evidence linking MC1R variation to any other neurodegenerative disease exists." (PMID 34584092, 2021).
neurological diseases (2 papers, 2021 to 2022). "Previous studies reported that activation of melanocortin-1 receptor (MC1R) exerts antioxidative stress, antiapoptotic, and neuroprotective effects in various neurological diseases." (PMID 35140838, 2022). "Activation of melanocortin-1 receptor (MC1R) has been shown to exert anti-inflammatory and neuroprotective effects in several neurological diseases." (PMID 33468172, 2021).
inflammation (1 paper, 2010). Aberrant reaction of the microcirculation characterized by movement of fluid and leukocytes from the blood into extravascular tissues. "However, in a murine model of DSS-induced experimental colitis MC-1R has been shown to play a role in intestinal inflammation since disease progression was aggravated in C57BL/6Je/e mice indicating that α-MSH/MC-1R mediated signaling is crucial for intestinal inflammation." (PMID 20126537, 2010).
MC1R also shares sentences with these, for which no sentence is quoted: oculocutaneous albinism (5 papers); familial melanoma (4); metastatic tumors (3); Arthritis (2); bipolar disorder (2); cancers of the lung (2); dental anxiety (2); Infertility (2); melanocytic nevus (2); mucosal melanoma (2); rheumatoid arthritis (2); schizophrenia (2); Sepsis (2); squamous cell carcinoma (2); subarachnoid hemorrhage (2); type 2 diabetes (2); acne vulgaris (1); anemia (1); Angelman syndrome (1); autoimmune disease (1); Basal cell nevus syndrome (1); Blepharophimosis (1); brain infarct (1); breast (1); Central hypothyroidism (1); colorectal tumors (1); congenital hypothyroidism (1); congenital nystagmus (1); Constitutional mismatch repair deficiency syndrome (1); cutaneous squamous cell carcinoma (1).
A further 60 diseases each share a sentence with MC1R in 1 paper.